MEN1 (menin 1)
Diseases named in the same sentence as MEN1 in open-access papers (continued):
Sharing a sentence is not in itself a finding about the gene and the disease.
tumor (continued). "Subsequent studies revealed that the vast majority of small MEN1 pNENs grow slowly with a growth velocity of approximately 1% per month or even less referring to tumor diameter reflecting a benign behavior." (PMID 37444604, 2023). "We interrogated the TGCA-CCA datasets to gain insight into the variation of MEN1 mRNA level as a function of tumor grade." (PMID 36782257, 2023). "To this end, we investigated the network starting states leading to the aggressive tumor attractors in both WT and MEN1 conditions (starting from a seed of 100 million randomly drawn starting states)." (PMID 37270586, 2023). "The MEN1 gene on chromosome 11 controls production of menin, which possesses a tumor-suppressive function." (PMID 37190177, 2023). "Inhibition of MEN1 neddylation or knockdown of CUL4 substrate receptor DCAF7 induced MEN1 protein accumulation and resulted in impeded malignant biological behaviors in vitro and reduced tumor volume in vivo." (PMID 37659057, 2023). "As mentioned in the familial PanNENs, MEN1 is a tumor suppressor, and it interacts with several proteins, receptors, and transcriptional factors." (PMID 36830839, 2023). "Efforts have demonstrated extensive work for multiple cell types in MEN1 deletions, providing valuable insights into tumor cell origin and fate." (PMID 37568572, 2023). "MEN1 is ubiquitously expressed and can either act as a tumor suppressor or facilitate tumor growth in a tissue-specific manner." (PMID 38003662, 2023). "The pancreas was the only tumor site predictive of MEN1 in patients with the first diagnosis of NET." (PMID 37761922, 2023). "Our data demonstrating the sensitivity of MM to loss of MEN1 are in line with previous analyses of loss-of-function screenings, where MM was ranked as the most MEN1-dependent tumor entity." (PMID 38003662, 2023). "MEN1 gene contains 10 exons that encode a 610-amino-acid protein called MENIN, which acts as a tumor suppressor." (PMID 36967793, 2023). "In one MEN1 syndrome tumor with aberrant menin staining (patient 16), LOH analysis showed a loss of chromosome 11q13.1, confirming the genetic loss of MEN1." (PMID 37199453, 2023). "Among patients with multiple tumors, 100% of patients with MEN1 syndrome and 21% of patients with non-MEN1 showed aberrant nuclear menin expression in at least one tumor." (PMID 37199453, 2023). "Originally described in the context of multiple endocrine neoplasia 1 (MEN1) as a tumor suppressor, it was later found that menin regulates hematopoiesis and myeloid transformation." (PMID 37296920, 2023). "Careful functional evaluation and determination of tumor imaging characteristics of adrenal lesions > 1 cm is important in MEN1, especially keeping in mind that ACC is > 10-fold more common among MEN1 adrenal lesions than among sporadic cases." (PMID 37409236, 2023). "Pathways enriched for hypermethylated genes in tumours developing in MEN1-knockout mice included those involved in the Wnt/beta-catenin pathway, with increased beta-catenin levels secondary to loss of Sox-regulatory proteins by promoter methylation." (PMID 37434653, 2023). "For example, the second isoform of MEN1, a tumor suppressor involved in many cancers, differs from the primary isoform by only five amino acids deleted at positions 149–153." (PMID 37563329, 2023). "First, the type and the probability of a developed tumor in the mouse model were different from those in humans, with a 40% probability of PNETs development in MEN1 patients but 79.2% in Men1-mutant rodents." (PMID 35954231, 2022). "Previous studies have used the Cre recombinase-loxP conditional knockout approach to study the tumor suppressor role of MEN1 gene in the pituitary glands and pancreas." (PMID 36552783, 2022). "We determined that three oncogenes, PD-L2, ETV5, and MTOR and 113 long intergenic non-coding RNAs (lincRNAs) were constantly up-regulated, whereas two oncogenes, BCR and GTF2I, one tumor suppression gene MEN1, and 30 lincRNAs were constantly down-regulated." (PMID 35317849, 2022).
tumor (continued). "Using immunoblot analysis, we found that the levels of γ-H2AX were higher in tumor samples derived from hTS/Men1–/– compared with Men1–/– mice." (PMID 36048542, 2022). "As pNENs were the most analyzed tumor in GEP-NEN (epi)genomics, and the genes MEN1, DAXX, and ATRX are the most frequently mutated in pNENs, we investigated their mutational status across racial groups via IHC analyses." (PMID 36969744, 2022). "Using these mouse models, we showed that overexpression of hTS in inactivated Men1 islet cells shortened the latency for tumor development and reduced survival of both hTS/Men1+/– and hTS/Men1–/– mice." (PMID 36048542, 2022). "In one patient (#5), tumor screening and follow-up were delayed and irregular after MEN1 diagnosis because he was working in another part of Finland." (PMID 35696052, 2022). "The jaw bone‐derived primary mesenchymal stromal cells isolated from the OF tumour (OFMSCs) showed a significant reduction of Men1 mRNA level and reduced ALP activity and mineralization." (PMID 35481717, 2022). "While MEN1 has long been known as a tumor suppressor gene, our novel findings vis-à-vis its involvement in cholinergic synapse formation and synaptic plasticity has since extended its role beyond tumorigenesis." (PMID 36552783, 2022). "We showed that elevated hTS in Men1-deleted tumor cells enhanced cell proliferation, deregulated cell cycle kinetics, and was associated with a higher frequency of somatic mutations, DNA damage, and genomic instability." (PMID 36048542, 2022). "In these studies, blockade of this pathway by various means, including the DHODH inhibitor leflunomide, attenuates cell growth and tumour progression, suggesting a critical dependence on DHODH specifically in MEN1-mutated tissue." (PMID 36694894, 2022). "The importance of screening has also recently been highlighted by a study of children and adolescent MEN1 patients, which indicated that 70% of patients developed a tumour before 18 years of age, including metastatic pancreatic NETs." (PMID 35900839, 2022). "Mouse models with conditional deletion of Men1 recapitulate the clinical features of PanNETs, including a long latency, suggesting that additional oncogenic events are required for tumor promotion." (PMID 36048542, 2022). "A large cohort of hTS/Men1–/– (n = 61) and Men1–/– (n = 68) as well as hTS/Men1+/– (n = 25) and Men1+/– (n = 24) mice were followed until death or when mice were required to be euthanized owing to symptoms of tumor burden per IACUC guidelines." (PMID 36048542, 2022). "It has been reported that MEN1 has dual roles in tumour suppression and proliferation in breast tumourigenesis." (PMID 35968938, 2022). "It is now recognized that thymic NETs, a rare but aggressive tumor, carry the highest odds ratio of death among MEN1 patients." (PMID 33716975, 2021). "Tumor size is an important predictive factor of prognosis and overall survival in MEN1 pNETs, mostly for NF-pNETs; tumors larger than 2 cm in diameter have been associated with a high risk of malignancy and metastases development." (PMID 33919851, 2021). "The authors observed that 21% of cluster 1 tumours also contained DAXX/ATRX alterations, again lending support to the concept that these mutations are late events in pNET pathogenesis driven by MEN1 loss." (PMID 34439335, 2021). "Tumours in subgroup T2 harboured more mutations in ATRX, DAXX and MEN1 with recurrent loss/LOH across 11 chromosomes." (PMID 33536587, 2021). "Other epigenetic regulators, including small non-coding microRNA, have also been postulated to contribute to the pathogenesis of tumor initiation among patients with MEN1." (PMID 33716975, 2021). "Patients should be discussed in multidisciplinary tumor boards with vast experience in MEN1-related dpNETs." (PMID 33521900, 2021). "Epigenetic factors are the main suspected co-actors in driving tumor development and progression in MEN1 target neuroendocrine cells." (PMID 34298972, 2021).
tumor (continued). "An early use of these compounds in patients with MEN1 is also suggested to prevent further tumor progression and development of endocrine syndrome." (PMID 34681263, 2021). "PDX1 had lower expression and hypermethylation in ATRX/DAXX/MEN1 mutant tumours (T2 and T3) than wild-type tumours (T1)." (PMID 33536587, 2021). "In MEN1, a clear clinical benefit was observed in functioning pNENs, in parallel with the control of tumor growth, which seemed to be higher in patients with an endocrine syndrome." (PMID 34681263, 2021). "Taken together, these data suggest a comparable activity and safety of SSAs for inherited and sporadic pNENs, but a higher rate of tumor shrinkage in MEN1, supporting their wide and early use in these patients." (PMID 34681263, 2021). "MEN1 is an extensively studied tumour suppressor gene, with well-defined functions in the endocrine tissue." (PMID 34943798, 2021). "For all these reasons, a diagnosis of MEN1 can be a psychological shock for the patient, as well as his/her relatives, more so than the diagnosis of a single tumor." (PMID 33407684, 2021). "Among the eleven downregulated miRNAs in Men1+/− three were known tumor suppressors (miR-486-3p, miR-330-5p and miR-214-5p) and these three were most highly ranked according to fold change (−1.33, −1.14 and −1.05, respectively)." (PMID 34285285, 2021). "Multiple endocrinous neoplasia (MEN) syndrome is characterized by the occurrence in the same patient of tumours (glandular hyperplasia and/or malignancy) of two or more endocrine glands, generally classified into four major forms (from MEN1 to MEN4)." (PMID 33809659, 2021). "We previously identified that the tumor suppressor gene, MEN1, regulates both the expression and synaptic targeting of α7 nAChRs in the mouse hippocampal neurons in vitro." (PMID 34943798, 2021). "Epigenetic factors, such as microRNAs (miRNAs), are strongly suspected to have a role in MEN1 tumor initiation and development." (PMID 34298972, 2021). "In addition, identification of these genetic modifiers and their roles may help to provide explanations for the heterogeneity and age-related penetrance of MEN1, as well as identifying tumour-associated pathways that may be targeted by anti-proliferative compounds." (PMID 32348957, 2020). "Of genes previously reported as commonly mutated in PNETs, only PDGFRA and MTOR were found to be mutated in a few tumor samples, and other genes, including ATM, ATRX, TSC2, DAXX, VHL, and MEN1, were mutated only in individual samples." (PMID 32586046, 2020). "Identical mutations can cause either MEN1 or FIHP in different families, thereby implicating a role for genetic modifiers in altering phenotypic expression of tumours." (PMID 32348957, 2020). "On the other hand, very few studies of miRNA expression analysis in tumor specimens from MEN1 patients have been conducted." (PMID 33066578, 2020). "Combined with the previous reports, the present study further define a pivotal tumor suppressor function of MEN1 in lung tumorigenesis." (PMID 32081882, 2020). "We screened MEN1, DAXX and ATRX genes for mutations and we classified DAXX/ATRX mutated samples, those tumours which are mutated in either or both the genes." (PMID 33288854, 2020). "The IPA findings presented in this paper must thus be carefully studied further, foremost in representative human tumor materials, before deciding on their actual biological and clinical relevance in MEN1 tumorigenesis." (PMID 32884006, 2020). "The aim of this review is to provide a general overview on the involvement of miRNAs in MEN1 tumor development, to be used as possible targets for novel molecular therapies." (PMID 33066578, 2020). "We therefore utilised this model to investigate the role of genetic background on tumour formation in adult Men1+/- mice, by carrying out backcrosses to generate Men1+/- mice on congenic C57BL/6 and 129S6/SvEv strain backgrounds." (PMID 32348957, 2020).
tumor (continued). "Both mouse models developed well-differentiated (WD) G1/G2 PanNETs at a much shorter latency than Men1 or Pten single deletion alone and exhibited histopathology of human MEN1-like tumor." (PMID 31160716, 2020). "The clinical behavior of MEN1 largely depends on tumor spread and histological features, as well as type and degree of hormone hypersecretion, risk of tumor recurrence, and duration of surveillance." (PMID 33312161, 2020). "Double heterozygous Men1 and Rb1 knockout mice have been reported to develop the same tumor spectrum as the respective single knockout mice." (PMID 32733644, 2020). "Although MEN1 is well recognized as a classical tumor-suppressor gene, subsequent studies found aberrant upregulation of the gene in solid tumors and leukemias." (PMID 32971831, 2020). "We do, however, consider our new cell line MEN1-KO-BON1 to be a useful tool for future in vitro tumor biology studies in the field of neuroendocrinology." (PMID 32884006, 2020). "The Endocrine Society clinical practice guidelines for MEN1 suggest surgical resection for NF-pNETs >1 cm in size, or tumors <1 cm in size with significant growth, such as doubling of tumor size over 3–6 months and exceeding 1 cm in size." (PMID 31263451, 2019). "Of the 31 centres reporting on the rare genetic tumour theme, 26% reported an international registry awareness for MEN1 and 9% reported participation." (PMID 30407922, 2019). "Subsequent BrdU incorporation assay revealed a significant decrease in tumor cell proliferation in KIF11-depleted Ben-Men-1 and NCH93 cells for both siRNAs employed." (PMID 30991738, 2019). "MEN1 to -3 are autosomal-dominant diseases associated with mutations in the MEN1 (MEN1) and RET (MEN2 and -3) genes, which act as tumor suppressor gene and an oncogene, respectively." (PMID 30990521, 2019). "The additional somatic MEN1 mutation of the normal allele (the second hit) predicts coding of an inactivated MENIN protein, leading to tumor development." (PMID 30899245, 2019). "Its indication for adolescents with MEN1-related HPT seems to be limited as one of its major drawbacks is the intensity of radiation exposure and the risk of future development of neoplasms in the surrounding tissues." (PMID 30899245, 2019). "Clinical manifestations of PITs in MEN1 are similar to those with sporadic PITs, and include those that are due to hormone excess, and those that are related to the size of the tumor." (PMID 31263451, 2019). "Parathyroid glands in HPT/MEN1 usually evolve to a neoplasm at different moments, depending on occasion that the second hit ensues in each gland." (PMID 30899245, 2019). "Here, we reported the results of the analysis of a large database of Florentine MEN1 patients from the Referral Centre for Hereditary Endocrine Tumours of the “Regione Toscana”, comparing our data with the previously published." (PMID 30428914, 2018). "This study also confirmed previous low-throughput studies on the frequent mutation of MEN1, and identified PTEN, another gene of the PI3K/mTOR pathway involved in the inhibition of PI3K, as a recurrently (7.3%) mutated tumour suppressor." (PMID 29321190, 2018). "The total RNA was extracted from proband tumor tissues and peripheral blood lymphocytes of III-6 and HC to identify the impact of splicing donor mutation on MEN1 transcription." (PMID 29416715, 2018). "According to the current practice guidelines genetic mutation analysis should be offered to all patients meeting the familial or clinical criteria for diagnosis of MEN1, and patients presenting with a MEN1 related tumor." (PMID 30254610, 2018). "Seventeen patients (14 women and 3 men) presented bronchopulmonary carcinoids (11.72% of MEN1 affected patients) with a mean age of tumour diagnosis of 47.3+ 12.5 years (range 26–73 years)." (PMID 30428914, 2018).
tumor (continued). "Molecular analysis of peripheral and/or tumor DNA in this cohort revealed germline mutations in the APC gene, MEN1 gene, and FH gene in three of the patients with AIMAH, who did not have a family history of CS." (PMID 30456751, 2018). "There is mounting evidence that intensive follow-up of MEN1 patients and screening for tumor manifestations reduces morbidity and improves survival." (PMID 30254610, 2018). "Does early onset of PHPT in MEN1 accompany tumor in fewer parathyroid glands? does early onset reflect an unusually aggressive course?" (PMID 30065698, 2018). "Adenomas of anterior pituitary gland affect about 30–40% of MEN1 patients and represent the third most common tumours in MEN1." (PMID 30428914, 2018). "Inactivation of MEN1, another well-known tumor suppressor of pNETs, together with of PHLDA3 is necessary for the development of pNET." (PMID 29121094, 2017). "More than 90% of tumors from MEN1 patients will have LOH of MEN1, with loss of menin expression, consistent with a tumor suppressor role for MEN1." (PMID 28881068, 2017). "MEN4 is a syndrome characterized by the same clinical heterogeneity and tumor spectra of MEN1, but also in a few cases by gonadal, adrenal, renal, and thyroid tumors." (PMID 29036195, 2017). "For example, menin, the product of the tumor-suppressor MEN-1 gene, represses JunD-FL transcriptional activity by interacting through its first 48 amino acids." (PMID 29379481, 2017). "As such, it provides important insights into the possible role of epigenetic mechanisms in the pathogenesis of MEN1 tumor development." (PMID 26871472, 2016). "The Men1+/− mice had magnetic resonance imaging at 12 and 21 mo, and from 20 mo oral 5-bromo-2-deoxyuridine for 1 mo, to assess tumor development and proliferation, respectively." (PMID 26990064, 2016). "Our study provides important insights into the role of menin in DNA methylation and its impact on the pathogenesis of MEN1 tumor development." (PMID 26871472, 2016). "We demonstrated that the expression and enzymatic activity of DNMT1 was significantly increased in tumor tissues from MEN1 patients, Men1 KO mice, and Men1 null cell lines." (PMID 26871472, 2016). "In conclusion, CDKN1B V109G polymorphism seems to play a role in the development of aggressive tumours in MEN1." (PMID 25824098, 2015). "To test if ARC contributes to MEN1 tumor development in the endocrine pancreas, we generated mice that lacked none, one, or both copies of ARC in the context of Men1 deletion." (PMID 26709830, 2015). "As previously reported, it should be noted that the genetic screening is helpful to anticipate the identification of MEN1 participants so detecting MEN1-related tumours at an early stage 28,29." (PMID 25824098, 2015). "More than 1336 different mutations (1133 germline and 203 somatic) have been reported 4, the majority of which are inactivating according to the notion that MEN1 is a tumour suppressor gene." (PMID 25824098, 2015). "The MEN1 gene responsible for MEN1 acts as a tumor suppressor gene, and tumors in MEN1 arise through the two-hit mechanism." (PMID 24959251, 2014). "Finally, a genetic diagnosis of MEN1 is made on identification of a germline MEN1 mutation in an individual, who may be asymptomatic and has not yet developed any of the serum biochemical or radiological abnormalities indicative of tumor development." (PMID 23933118, 2014). "Previous studies of loss of heterozygosity (LOH) by microsatellite analysis in tumor tissues of MEN1 patients have supported a tumor suppressor function of the MEN1 gene." (PMID 24959251, 2014).